Y_RNA (Y RNA )
Gene: Miscellaneous RNA gene on chromosome X (86,019,608 to 86,019,715, forward strand). Ensembl gene ENSG00000199567.
Homologues: Orthologues: chimpanzee Y_RNA (100% identical), macaque Y_RNA (94% identical). Paralogues in human: Y_RNA (87% identical), Y_RNA (86% identical), RNY3 (85% identical), Y_RNA (85% identical), Y_RNA (84% identical), Y_RNA (83% identical), RNY3P1 (82% identical), RNY3P16 (82% identical), Y_RNA (82% identical), RNY3P14 (81% identical), Y_RNA (81% identical), RNY3P10 (80% identical), and 93 more.